CD4 (CD4 molecule)
Diseases named in the same sentence as CD4 in open-access papers (continued):
Sharing a sentence is not in itself a finding about the gene and the disease.
latent infection (continued). "Furthermore, infection causes a significant reduction in the number of CD4 + T cells, CD8 + T cells, B cells, NK together with lymphocytes, monocytes and eosinophils, with immunosuppression and increased susceptibility to infection and reactivation of latent infections." (PMID 35578290, 2022). "In HIV, CD4+ TRM have now been shown to be a major target for productive and latent infection in the cervix." (PMID 33668777, 2021). "As such, chemotactic stimulation, such as stimulating resting CD4 T cells with the chemokines CCL19/CCL21, has been shown to activate the cofilin pathway and thereby promote HIV latent infection of resting T cells." (PMID 34765923, 2021). "In contrast to CD2 signaling, prestimulation of resting CD4 T cells with anti-CXCR4 antibody, with the chemokines CCL19/CCL21, or with IP-10 (CXCL10) has been shown to promote HIV-1 latent infection of resting CD4 T cells." (PMID 34765923, 2021). "CD4 T cell death or survival following initial HIV infection is crucial for the development of viral reservoirs and latent infection, making its evaluation critical in devising strategies for HIV cure." (PMID 33643305, 2020). "This help from recovered CD4 T cells restores the long-term functionality of the CD8 T cells and prevents the reactivation of the latent infection." (PMID 31119107, 2019). "We observed that R10015 blocked X4 HIV-1 latent infection of resting CD4 T cells; we also observed R10015 dose-dependent inhibition of R5 HIV latent infection of resting memory CD4 T cells." (PMID 28381571, 2017). "The combination of age and CMV latent infection has been proven to have a profound impact on the immune phenotype and function of T-cells, not only on the CD8+ subset but also on CD4+, NKT-like, and γδ T-cells." (PMID 28626460, 2017). "In our viral latent infection system, total resting CD4 T cells or the CD45RO+ RA− memory CD4 T cells were purified from the peripheral blood, cultured overnight without stimulation, and then treated with R10015 for 1 h." (PMID 28381571, 2017). "Reactivation of this latent infection occurs in immunocompromised patients and is very common in AIDS patients with CD4 T cell counts below 200/μL." (PMID 29163509, 2017). "In fact, reactivation of several latent infections, including HBV infection, is facilitated by immune reconstitution, and our patient experienced a relevant increase in CD4 cell count when comparing values before and after DAA treatment." (PMID 28249574, 2017). "In contrast, in resting CD4+ T-cells alone, R5-tropic HIVNL4.3(AD8).EGFP with a TCID50 of ≥5 typically established productive and latent infection in most donors." (PMID 27383184, 2016). "Predicted numbers of CD4+ and CD8+ T cells (including the subsets of Mtb-specific T cells) in blood were generated for 43 virtual NHP (20 latent infection, 23 active TB as in the experimental NHP dataset)." (PMID 27065304, 2016). "We demonstrated that while X4-tropic HIV can infect unstimulated resting CD4+ T-cells, up to half of the donors required the presence of CCL19 to establish latent infection." (PMID 27383184, 2016). "Compared to αCD3/αCD28-stimulated cells at 6 days postinfection, untreated resting CD4+ T cells showed significantly lower levels of HIV infection but, nonetheless, permitted both productive and latent infection." (PMID 26067822, 2015). "These UL138-specific CD4+ T cells are able to mediate MHC class II restricted cytotoxicity and, importantly, show IFNγ effector function in the context of both lytic and latent infection." (PMID 24130479, 2013). "Collectively, the human TG represents an immunocompetent environment for both CD4 and CD8 T-cell recognition of HSV-1 proteins expressed during latent infection." (PMID 23966859, 2013). "The frequency of latent infection, expressed as infectious units per million (IUPM) resting CD4+ T cells, is determined using Poisson statistics." (PMID 23737751, 2013).
latent infection (continued). "As a comparison to latent infection, cultures of PBMC and enriched CD4+ T-cells from infected cats were activated with mitogens ex vivo, confirmed to be transcriptionally active (detectable FIV gag RNA and 2-LTR circle junction DNA), and then examined by ChIP." (PMID 22754653, 2012). "When assessing cytokine profiles, PPD specific CD4 T cells secreting both IFN-γ and IL-2 predominated in treated TB, latent infection and BCG-vaccination, whilst in active TB the cytokine profile was shifted towards cells secreting IFN-γ only (p<0.0001)." (PMID 21423578, 2011). "Some have found that productively infected activated CD4 + T cells decay rapidly and are unlikely to form latent reservoir, and others showed latent infection occurs in non-dividing CD4 + T cells rather than activated and proliferating CD4 + T cells." (PMID 37202790, 2023). "We have demonstrated in our EC stimulation model that EC could render resting CD4 + T cells permissible for HIV infection, including latent infection." (PMID 37202790, 2023). "In this study, we infected in vitro activated CD4 + T cells at day 7 post-activation rather than day 3, and we still did not detect latent infection." (PMID 37202790, 2023). "From our previous work, we observed that activated CD4 + T cells do not harbor latent infection after in vitro infection." (PMID 37202790, 2023). "While primary MP and CD4+ T cells and transformed cell lines are used to interrogate mechanisms of HIV-1 persistence, they often fail to accurately reflect the host cells and tissue environments that carry latent infections." (PMID 37513726, 2023). "Our own data showed the lack of latent infection in activated CD4 + T cells when they were infected at the peak of their activation." (PMID 37202790, 2023). "Some found there to be a latent reservoir in the activated CD4 + T cells although resting cells displayed a higher propensity for latent infection, while others found there to be no latent infection in activated CD4 + T cells." (PMID 37202790, 2023). "Additionally, we observed strong CD4 and CD8 T cell responses to the herpesviruses CMV and EBV in pwMS, suggesting that specific T cell responses against antigens from long-term latent infections are present." (PMID 37159281, 2023). "In summary, all these combined results demonstrated that among CD4 T cells, derived from our in vitro culture system, HIV latent infection was generated at a higher frequency in those cells that become only minimally activated while in the presence of fully activated and productively infected cells." (PMID 35895672, 2022). "To examine the innate immune landscape in latent cells we utilized multiple cell line models of HIV latent infection, including two different Jurkat CD4 + T cell latency models, JLat9.2 and JLat11.1, and the CEM CD4 + T cell ACH2 latency model, each harboring silent HIV provirus." (PMID 35804422, 2022). "Our experimental observations are consistent also with previous reports that show most infected cells in humans and macaques do not have an activated phenotype, and that naïve CD4 T cells can contain latent infection in vivo." (PMID 35895672, 2022). "Moreover, treatment of resting CD4+ T cells with a LIM kinase inhibitor R10015 blocked cofilin phosphorylation and abrogated IP-10-mediated enhancement of HIV latent infection." (PMID 34447368, 2021). "To directly test whether FKBP3 promotes HIV-1 latency in primary human CD4+ T lymphocytes, we established a primary HIV-1 latent infection model (primary CD4+ T lymphocyte cells from three donors)." (PMID 34281390, 2021). "The establishment of a latent infection by HCMV is a common event likely correlated to immunosenescence by increasing the levels of highly differentiated effector memory cells in the CD8+ and CD4 + T-cell pools." (PMID 33874975, 2021).
latent infection (continued). "In this mouse latent infection model, we found that CD4 T-cells were important for control of the pulmonary infection and mirrored clinical findings in advanced HIV patients with low CD4 T-cell counts that develop cryptococcal meningitis." (PMID 35186781, 2021). "However, given that CD2 prestimulation led to an opposite, strong inhibition of HIV-1 latent infection, we felt compelled to investigate the effects of CD2 stimulation on cofilin activation in resting CD4 T cells." (PMID 34765923, 2021). "Furthermore, herpes simplex virus promotes CXCR3-mediated migration of CD4+ T cells to sites of infection and CD8+ T cells to sites of latent infection." (PMID 33912186, 2021). "Host responses in controlling the latent infection may include macrophage activation, maintenance of granuloma structure, and expression of IFN-γ, TNF-α, CD4 T cells, and CD8 T cells." (PMID 31992621, 2020). "We have previously reported that HIV infection of resting CD4+ T cells in vitro, in the presence of mDCs and monocytes but not pDCs, enhanced the establishment of latent infection in CD4+ T cells." (PMID 32109259, 2020). "Given that pDC produce abundant type I IFN and type III IFNs, here we investigated how pDC modulate HIV latency in CD4+ T cells and studied the effect of individual type I and III IFNs on the establishment of latent infection as well as the effect of different IFNs on latently infected cells." (PMID 32109259, 2020). "Co-culture of resting CD4+ T cells with irradiated mDCs did not significantly change the level of productive and latent infection, indicating that mDCs facilitate infection via a cell-cell interaction rather than via mDC-secreted soluble factors." (PMID 32109259, 2020). "Finally, to examine the apoptotic effects of BL-V8-310 on human primary CD4+ T-cells latently infected with HIV, the CCL19-stimulated primary cell model of latent infection was employed." (PMID 30413535, 2019). "Latency has also been shown to occur following direct infection of resting CD4+ T cells, but it is not yet known which subsets of resting CD4+ T cells are involved in the latent infection by X4 and R5 HIV-1." (PMID 31036079, 2019). "Our results also revealed differences between IFNG and TNFA induction profiles and greater proportions of CD4+CD69+ T cells producing TNFA (but not IFNG) during active TB relative to latent infection." (PMID 30283456, 2018). "In our 2017 study, we demonstrated that soluble factors secreted by EC can promote both productive and latent infection of resting CD4+ T cells, though not to the same level as stimulation by cell-cell contact." (PMID 30285810, 2018). "Since NRON showed higher expression level in resting CD4+ T lymphocytes than in activated cells, we sought to determine whether this lncRNA functions in HIV-1 latent infection." (PMID 27291871, 2016). "mDCs potently induced productive and latent infection of resting CD4+ T-cells at all titres of R5-tropic HIVNL4.3(AD8).EGFP, demonstrating the high efficiency of this system to facilitate infection of resting CD4+ T-cells." (PMID 27383184, 2016). "However, our data support a model in which virus-specific CD4 + and CD8 + T cells synergistically contribute to the quantity and quality of the memory T-cell response during latent infection in aging." (PMID 26778409, 2016). "Five days following infection, non-proliferating (eFluor670hiEGFP−) CD4+ T-cells were sorted from the APC-T-cell co-cultures to quantify latent infection." (PMID 26362311, 2015). "In contrast, the levels of latent infection did not change between untreated total lymphoid cells and untreated CD4+ T cells from each tissue." (PMID 26067822, 2015). "Together these data show that only CD1c+mDC, SLAN+ DC and CD14+ monocytes were able to establish post-integration latent infection in non-proliferating CD4+ T-cells, while B-cells and CD141+ mDC were able to establish pre-integration latent infection." (PMID 26362311, 2015).
latent infection (continued). "However, in vitro latent infection can occur following the reversion of a HIV-1 infected, activated CD4+ T-cell to a resting state." (PMID 26362311, 2015). "We have previously reported that mDC, but not pDC, are able to efficiently induce post-integration latent infection in resting CD4+ T-cells using an in vitro DC-T-cell co-culture model." (PMID 26362311, 2015). "In particular, we will discuss the role of CD4 and CD8 T cells in contrasting the advance of the intracellular pathogen in already infected people or the progression to active disease in subjects with latent infection." (PMID 24795723, 2014). "Naïve human CD4+ T cells were isolated, activated in a non-polarizing environment, infected with the gGnΔ virus, and then cultured for seven days to establish a latent infection." (PMID 24156270, 2013). "Supernatants from infected mDC-T cell co-cultures did not facilitate the establishment of latency, consistent with cell-cell contact and not a soluble factor being critical for mediating latent infection of resting CD4+ T cells." (PMID 24339779, 2013). "Collectively, the data indicate that the human TG is an immunocompetent environment for CD4 and CD8 T-cell recognition of diverse HSV-1 proteins expressed during latent infection and that the viral antigens identified herein are rational candidates for HSV-1 subunit vaccines." (PMID 23966859, 2013). "It is unclear why CD4+ T cell responses to HCMV lytic antigens appear to be dominated by IFNγ producing cells, while CD4+ T cells, which recognise antigens, expressed during latent infection predominantly secrete cIL-10." (PMID 24130479, 2013). "Consistent with our previous work, incubation of resting CD4+ T-cells with CCL19 followed by infection with WT NL4.3 resulted in high levels of viral integration and minimal production of RT in the supernatant, consistent with latent infection." (PMID 21992606, 2011). "Our results confirmed that only the genuine HIV-1 envelope protein, but not VSV-G, is capable of mediating latent infection of resting CD4 T cells." (PMID 19851458, 2009). "In addition to the virus exposure, there are many other factors influencing the latent infection of the resting CD4 + T cells, as some of the negative control cells activate the immune factors." (PMID 35967854, 2022). "As the main reservoir of latent HIV-1 in infected individuals comprises resting CD4+ T cells, we ex vivo infected, without prior activation, CD4+ T cells obtained from healthy donors with a defective full-length HIV-1 virus harboring a luciferase reporter to establish latent infections." (PMID 35640596, 2022). "The exhaustion status of CD4 T cells is mediated by the increased expression of the transcription factor BLIMP-1, and deletion of this molecule led to the restoration of CD4 T cell function, reversal of CD8 exhaustion and prevention of reactivation of the latent infection." (PMID 31119107, 2019). "Using RNA-seq and Illumina gene expression microarrays, we also identified potential mediators of latent infection expressed by APC that could induce latency in the non-proliferating CD4+ T-cells during APC-T cell interactions." (PMID 26362311, 2015). "Importantly, productive and latent infection of resting CD4+ T cells over the 6-day time-course was not the result of replication-competent virus being present in our HIV Duo-Fluo I viral stocks." (PMID 26067822, 2015). "Gene expression in non-proliferating CD4+ T cells, enriched for latent infection, showed significant changes in the expression of genes involved in cellular activation and interferon regulated pathways, including the down-regulation of genes controlling both NF-κB and cell cycle." (PMID 24339779, 2013). "In the fourth patient, the frequency of latent infection was very low (less than 1 infected cell in 5 million resting CD4+ T cells), and the activity of Pam3CSK4 could not be assessed." (PMID 24156240, 2013).
latent infection (continued). "Thus, neither the expression of CD27 on bulk CD4 T lymphocytes, nor the frequency of Mtb-specific IFN-γ producing CD4 T cells, discriminated active TB from latent infection." (PMID 22937086, 2012). "Thus, we examined the ability of VSV-G-pseudotyped HIV-1 to establish latent infection of resting CD4 T cells in the absence of HIV coreceptor signaling." (PMID 19851458, 2009). "In this report, we demonstrated a fundamental difference between the HIV-1 envelope and VSV-G in mediating HIV-1 latent infection of primary resting CD4 T cells, namely that only the HIV-1 envelope but not VSV-G is capable of supporting HIV latent infection of resting T cells." (PMID 19851458, 2009). "That western blot could not detect Dicer expression in monocytes, as compared to T-cells, is interesting as CD4+ T-cells support latent infection in HIV, but monocytes and macrophages do not." (PMID 17663774, 2007). "Moreover, as has been reported before, we also believe that the IGRA positivity may have been influenced by the relatively low CD4 counts, due to which we may have misclassified some LTBI− individuals with latent infections, especially in the case of the HIV-positive groups." (PMID 41148837, 2025). "Thus, Treg suppress CD4+ but not CD8+ T cells in the SG during latent infection." (PMID 28796839, 2017). "However, while many in vitro latency models rely on CD4+ T cells that were initially differentiated via T-cell receptor (TCR) stimulation into memory/effector cells, latent infection of naïve resting CD4+ T cells maintained under HSP conditions has not been fully addressed." (PMID 27990142, 2016). "Our results show that multiple blood derived mDC subsets can induce latent infection in non-proliferating CD4+ T-cells, suggesting that this observation may extend to other DC and myeloid lineage cells, such as LC and dermal DC (DDC) though they may have different ontogeny." (PMID 26362311, 2015). "One limitation to our conclusions about the latent infection is that they apply only to CD69−CD25−HLA-DR− infected CD4+ T cells in blood, which may not truly represent the latent pool, but may be a heterogeneous population containing truly latently infected cells as a small subset." (PMID 22496643, 2012). "Thus, efficient HIV transmission from DCs to CD4+ T cells through infectious synapses may play a central role not only for the massive expansion of HIV following initial infection, but also for generating latent infection in HIV-specific memory CD4+ T cells." (PMID 19180188, 2009). "In contrast, in activated CD4 + T cells cultured alone, PMA/I treatment did not increase GFP expression (p = 0.99), confirming the lack of latent infection." (PMID 37202790, 2023). "This was established by our findings which showed that transfer of non-exhausted antigen-specific CD4 T cells to chronically infected mice reversed the CD8 dysfunctionality and prevented the reactivation of the latent infection." (PMID 31119107, 2019). "Although we did not perform CD4+ lymphocyte count of HIV positive pregnant women, there is a chance of reactivation of latent infection with a possibility of congenital transmission." (PMID 23442946, 2013). "For latent infections of HIV and M. tuberculosis, there has not been a detectable chronic increase in cytokines compared to HIV alone; however, there is an increase in T cell activation markers on both CD4+ and CD8+ T cells, namely CD38+ and HLA-DR expression." (PMID 38731913, 2024). "Furthermore, treatment of chronically infected host with antigen-specific non-exhausted CD4 T cells can restore CD8 T cell functionality and prevent reactivation of the latent infection." (PMID 31119107, 2019). "Also, we demonstrated that treatment of toxoplasma-infected animals with surrogate marker-specific non-exhausted CD4 population reversed CD8 exhaustion and controlled the reactivation of latent infection." (PMID 29163509, 2017).